RPN2 (ribophorin II)
Description:
Subunit of the oligosaccharyl transferase (OST) complex that catalyzes the initial transfer of a defined glycan (Glc(3)Man(9)GlcNAc(2) in eukaryotes) from the lipid carrier dolichol-pyrophosphate to an asparagine residue within an Asn-X-Ser/Thr consensus motif in nascent polypeptide chains, the first step in protein N-glycosylation. N-glycosylation occurs cotranslationally and the complex associates with the Sec61 complex at the channel-forming translocon complex that mediates protein translocation across the endoplasmic reticulum (ER). All subunits are required for a maximal enzyme activity.
Synonyms: RPN-II; SWP1; RPNII; RIBIIR
Tractability: Small molecule: a structure with a bound ligand is known. Antibody: UniProt predicts a signal peptide or a membrane-spanning region. PROTAC: UniProt records ubiquitination sites on it; ubiquitination databases record sites on it; its protein half-life has been measured.
Gene: Protein-coding gene on chromosome 20 (37,178,396 to 37,241,624, forward strand). Ensembl gene ENSG00000118705.
Subcellular location: Endoplasmic reticulum; Endoplasmic reticulum membrane
Subcellular location (Human Protein Atlas): Endoplasmic reticulum
Pathways (Reactome):
Disease: Maturation of DENV proteins; Maturation of spike protein
Metabolism of proteins: Asparagine N-linked glycosylation; SRP-dependent cotranslational protein targeting to membrane
Cell-Cell communication: Regulation of CDH1 posttranslational processing and trafficking to plasma membrane
Immune System: PD-L1(CD274) glycosylation and translocation to plasma membrane
Gene Ontology:
Molecular function: protein binding; dolichyl-diphosphooligosaccharide-protein glycotransferase activity
Biological process: protein N-linked glycosylation; protein modification process
Cellular component: endoplasmic reticulum; membrane; oligosaccharyltransferase complex; oligosaccharyltransferase complex A; oligosaccharyltransferase complex B; endoplasmic reticulum membrane
Genetic constraint (gnomAD): Loss-of-function variants: 28 observed, 70.3 expected, observed/expected ratio (o/e) 0.4, 90% interval 0.29 to 0.55. The upper end of that interval is the gene's LOEUF score, 0.55, which puts it in group 2 of 6, group 1 being the genes least tolerant of losing a copy. Missense variants: 714 observed, 801.83 expected, observed/expected ratio (o/e) 0.89, 90% interval 0.84 to 0.95. Synonymous variants: 306 observed, 317.16 expected, observed/expected ratio (o/e) 0.96, 90% interval 0.88 to 1.06.
Homologues: Orthologues: chimpanzee RPN2 (99% identical), macaque RPN2 (99% identical), dog RPN2 (95% identical), guinea pig RPN2 (95% identical), pig RPN2 (94% identical), rat Rpn2 (94% identical), rabbit RPN2 (93% identical), mouse Rpn2 (92% identical), tropical clawed frog rpn2 (73% identical), zebrafish rpn2 (67% identical), Drosophila melanogaster OstDelta (33% identical), Caenorhabditis elegans ostd-1 (17% identical).
Diseases named in the same sentence as RPN2 in open-access papers:
RPN2 is named in the same sentence as 47 diseases in open-access papers, as found by Europe PMC text mining. Sharing a sentence is not in itself a finding about the gene and the disease. The quoted sentences say what the papers report.
breast carcinoma (34 papers, 2011 to 2025). "Accumulating studies have reported that RPN2 is implicated in multiple cancers, such as breast cancer, small-cell lung cancer, bladder cancer, and colon carcinoma." (PMID 38302629, 2024). "Silencing of ribophorin II reportedly facilitates the docetaxel-dependent apoptosis and cell growth inhibition of human breast cancer cells by reducing the N-linked glycosylation and membrane localization of P-glycoprotein." (PMID 34512323, 2021). "RPN2 is an important molecular marker in various cancers and has been associated with drug resistance in solid cancers, including breast cancer, oesophageal squamous cell carcinoma, non-small-cell lung cancer, and gastric cancer." (PMID 29069815, 2017). "RPN2 is also associated with the migration and invasion in cancers, including breast cancer, laryngeal squamous cell carcinoma, and gastric cancer." (PMID 29069815, 2017). "This study further demonstrated that the RPN2 expression status in patients with breast cancer was associated with the response to docetaxel, proposing RPN2 as a candidate predictive marker for resistance to docetaxel-based chemotherapy." (PMID 25789057, 2015). "Taken together, these results indicated that high glycosylation of CD63 by RPN2 is implicated in clinical outcomes in breast cancer patients." (PMID 24884960, 2014). "Previous studies have demonstrated that RPN2-mediated glycosylation of CD63 correlates with the malignancy of breast cancer cells." (PMID 40963867, 2025). "RPN2 was found to promote the malignant progression of breast cancer, gastric cancer and colon cancer." (PMID 36439123, 2022). "Accumulating studies have verified that RPN2 acted as an oncogene in many types of cancers, for example, colon cancer, breast cancer, esophageal cancer, and nasopharyngeal carcinoma." (PMID 35156537, 2022). "Ribophorin II (RPN2), a part of the N-oligosaccharyltransferase complex, promotes breast cancer malignancy by regulating the glycosylation of tetraspanin protein CD63 and multidrug resistance protein 1 (MDR1)." (PMID 35216622, 2022). "For example, RPN2 expression was positively correlated with clinically aggressive features of breast cancer, and it contributed to the initiation and metastasis of breast tumor." (PMID 35156537, 2022). "Based on the report of RPN2 physical interaction and subsequent functional suppression in breast cancer, we explored role of RPN2 in the GSK-3β/wnt/β-catenin pathway." (PMID 33087705, 2020). "This type of RPN2-mediated glycosylation of p-gp (encoded by MDR1) is responsible for the treatment resistance of several tumors, including breast cancer, ovarian cancer, gastric cancer, and esophageal squamous cell carcinoma." (PMID 33087705, 2020). "The expression of RPN2 is clinically relevant, showing a positive correlation with the degree of aggressiveness of breast cancers in patients." (PMID 31810196, 2019). "Accruing studies suggested RPN2 as an oncogene in multiple cancers, including breast cancer, colon carcinoma, nasopharyngeal carcinoma and esophageal cancer." (PMID 31888753, 2019). "Previous studies reported that the expression of RPN2 is increased in breast cancer, gastric cancer, colon cancer, nasopharyngeal carcinoma, and non-small-cell lung cancer." (PMID 30940778, 2019). "RPN2 was identified as a gene that confers docetaxel resistance to breast cancers by regulating, as a part of OST, the N-glycosylation of the P-glycoprotein and CD63." (PMID 31810196, 2019). "Analogously, RPN2 knockdown induced docetaxel-dependent apoptosis and cell growth inhibition in human breast cancer cells by reducing glycosylation of the P-glycoprotein with N-linked glycosylation, as well as decreasing membrane localization." (PMID 29069815, 2017).
breast carcinoma (continued). "It was previously reported that RPN2-knockdown promoted GSK3β-mediated suppression of heat shock proteins (HSP) in human breast cancer cells." (PMID 29069815, 2017). "We have also recently demonstrated that RPN2 regulates cancer stem cell properties through the functional suppression of glycogen synthase kinase 3β (GSK3β) in breast cancer cells." (PMID 25595901, 2015). "RPN2 is a key regulator in modulating DTX sensitivity in breast cancer cells through the glycosylation of P-glycoproteins." (PMID 25595901, 2015). "A previous study revealed that downregulation of RPN2 efficiently induced apoptosis in docetaxel-resistant human breast cancer cells in the presence of docetaxel." (PMID 25789057, 2015). "Currently, we are conducting a clinical phase I study of siRNA targeting RPN2 in advanced breast cancer patients in Japan and anticipate that this study will generate novel information that will be useful for NSCLC treatment." (PMID 25595901, 2015). "Previously, we demonstrated that ribophorin II (RPN2), which is part of the N-oligosaccharyl transferase complex, regulates docetaxel sensitivity and tumor lethal phenotypes in breast cancer." (PMID 25595901, 2015). "It has been proposed that RPN2 expression status is a predictive marker for drug resistance in breast cancer." (PMID 25789057, 2015). "RPN2 silencing induced docetaxel-dependent apoptosis and cell growth inhibition of human breast cancer cells through the reduction of P-glycoprotein glycosylation." (PMID 24884960, 2014). "Recently, we determined that RPN2 efficiently induced apoptosis in docetaxel-resistant human breast cancer cells." (PMID 24884960, 2014). "In this study, we demonstrate that RPN2 promotes cancer cell malignancy in breast cancer cells through the regulation of CD63 glycosylation." (PMID 24884960, 2014). "Our previous investigation had shown that expression of RPN2 mRNA in docetaxel-sensitive breast cancer cells was markedly and dose-dependently induced by docetaxel." (PMID 25181275, 2014). "The downregulation of RPN2 most efficiently induces apoptosis of drug-resistant breast cancer cells in the presence of docetaxel." (PMID 24212663, 2011). "RPN2-specific siRNA significantly suppressed tumor growth, suggesting that RPN2 may serve as a novel therapeutic target for overcoming drug resistance in breast cancer." (PMID 40963867, 2025). "In addition, another study reported that downregulation of the RPN2 gene effectively induced apoptosis in docetaxel-resistant breast cancer cells (MCF7–ADR cells)." (PMID 40963867, 2025). "RPN2 promotes docetaxel resistance in breast cancer cells by mediating CD63 glycosylation." (PMID 36439123, 2022). "Downregulation of ribophorin II has been reported to inhibit cancer cell proliferation and metastasis in osteosarcoma, lung cancer, and breast cancer." (PMID 34512323, 2021). "Studies on the relationship between RPN2 and breast cancer/gastric cancer have been published; however, until now, there have been no studies on the association between RPN2 and locally advanced or advanced head and neck squamous cell carcinoma." (PMID 34575229, 2021). "Ribophorin II (RPN2) is a protein component of an N-oligosaccharyl transferase complex, the downregulation of which can trigger apoptosis in human breast cancer cells resistant to docetaxel., and its silencing confers sensitivity of the tumor to cisplatin treatment." (PMID 32404045, 2020). "Besides its correlation with myeloid disturbance, RPN2 has also been identified as an indicator of prognosis in human pancreatic and breast cancer." (PMID 32404045, 2020). "The knockdown of Rpn2 induced cell cycle arrest in therapy-resistant breast cancer cells." (PMID 31456945, 2019).
breast carcinoma (continued). "Inhibition of RPN2 expression was found to reduce breast cancer malignancy by reducing CD63 glycosylation and modulating translocation of CD63, which is a cell surface glycoprotein with N-linked glycosylation that regulates cell motility, invasion, and cell signaling of tumors." (PMID 29069815, 2017). "However, in additional to mediating EGFR glycosylation, RPN2 can physically interact with both Y216-phosphorylated and unphosphorylated GSK3β to regulate the malignancy of breast cancer." (PMID 29069815, 2017). "Furthermore, studies have shown that RPN2 knockdown can inhibit cancer cell proliferation in osteosarcoma, non-small cell lung cancer, and breast cancer." (PMID 29069815, 2017). "Although the molecular mechanism underlying the cell invasiveness related to RPN2 remains unknown, our recent study reported that glycosylated CD63 by RPN2 plays an important role in breast cancer cell invasiveness by regulating MDR1 localization." (PMID 25595901, 2015). "A recent study identified ribophorin II (RPN2), part of an N-oligosaccharyl transferase complex, as a novel regulator of drug resistance via the regulation of the N-linked glycosylation of ABCB1 (P-glycoprotein) in breast cancer." (PMID 24212663, 2011). "However, glioma, breast cancer, and head and neck cancer cells with stem cell characteristics were reported to have decreased proteasome activity and reduced levels of the Rpn2 subunit of the 19S regulator but exhibited increased self-renewal capacity and tumorigenicity." (PMID 31456945, 2019). "Furthermore, the importance of RPN2 in tumor prognosis and therapeutic implications has been documented in other solid cancers, including esophageal squamous cell carcinoma, osteosarcoma and breast cancer." (PMID 26388988, 2015). "EEF1A2 and RPN2 are both located in 20q, and EEF1A2 has been suggested to be an oncogene and a diagnostic marker in various cancers, but has to our knowledge not previously been linked to sarcomas, whereas RPN2 has been shown to confer drug resistance in breast cancer." (PMID 23144859, 2012). "Our study showed that the expression of several OST subunits including RPN1, RPN2, STT3A STT3B, and DDOST were upregulated in breast cancer samples." (PMID 34778038, 2021). "Our current results indicate that CD63 glycosylation by RPN2 is important for the localization of CD63 and MDR1 in human breast cancer cells." (PMID 24884960, 2014). "Previously, we reported that ribophorin II (RPN2), which is part of an N-oligosaccharyle transferase complex, is responsible for drug resistance in breast cancer cells." (PMID 24884960, 2014). "We previously demonstrated that silencing of ribophorin II (RPN2), which is part of the N-oligosaccharyl transferase complex, efficiently induced apoptosis and reduced resistance to docetaxel in human breast cancer cells." (PMID 25181275, 2014). "RFS of the RPN1, RPN2, STT3A, STT3B, and DDOST with different molecular subtypes in breast cancer." (PMID 34778038, 2021). "Ribophorin II (RPN2) is a prognostic marker and has been shown to contribute to resistance against chemotherapeutic agents in human breast tumors and animal models of breast cancer." (PMID 25310523, 2014). "Considering that RPN1 and RPN2 belong to the same family of proteins, and that RPN2 functions in various tumors, we therefore hypothesized that RPN1 might be a carcinogenic gene in breast cancer." (PMID 38302629, 2024).
glioma (12 papers, 2019 to 2025). A benign or malignant brain and spinal cord tumor that arises from glial cells (astrocytes, oligodendrocytes, ependymal cells). "In glioma, tumor progression was associated with the suppression of miR-378e and consequent expression of ribophorin-II (RPN2), a target of miR-378e that promotes increased ROS and glycolysis." (PMID 36901722, 2023). "In conclusion, we, for the first time, revealed RPN2 upregulation in glioma tissues and GBM cell lines, which is negatively associated with clinical prognosis." (PMID 33087705, 2020). "There was statistically significant difference between primary and recurrent gliomas, suggesting that RPN2 was linked to the glioma progression." (PMID 33087705, 2020). "In the present study, we confirmed that RPN2 is prominently upregulated in gliomas and is significantly associated with WHO grade and poor clinical prognosis." (PMID 33087705, 2020). "By combining in vitro and in vivo experiments, we confirmed that the regulatory mechanism of circNFIX was associated with miR-378e/RPN2 axis in glioma." (PMID 31888753, 2019). "All these data indicated that the RPN2 overexpression leads to a markedly worse outcome and may act as a key oncogene implicated in glioma initiation and progression." (PMID 33087705, 2020). "Here, we identified a novel ER stress and UPR-driven gene signature, ESURATAG, composed of six genes (DERL2, RPN2, SEC13, SEC61A1, SEC61B, and STT3A) that are significantly upregulated in gliomas from older patients and strongly linked to tumor aggressiveness." (PMID 40718795, 2025). "Simultaneously, the researchers discovered that the level of circNFIX was increased in glioma tissue, which protected RPN2 mRNA from degradation in gliomas via sponging miR-378e, thus improving glucose metabolism in glioma cells." (PMID 40723354, 2025). "In gliomas, miR-378e targets RPN2, suppressing its oncogenic functions, for example, by inhibiting ROS production." (PMID 36901722, 2023). "For example, the highly expressed circNfix in glioma can act through the circNfix/miR-378e/RPN2 axis or be a sponge for miR-34a-5p and upregulate the target gene NOTCH1 to enhance glioma invasion through the Notch signaling pathway." (PMID 34745938, 2021). "Expression levels of risk factors BRCA1, DNM1L, RCN1, HSPB1, RPN2, LRRK2 and SPP1 in high‐grade gliomas were greater than those in lower‐grade gliomas, while the protein expression levels of protective factor PDIA3 were exactly the opposite." (PMID 33611848, 2021). "The analysis results showed that RPN2 was remarkably overexpressed in both primary and recurrent gliomas, especially primary GBM compared with the normal and lower grade samples (p < 0.0001)." (PMID 33087705, 2020). "Given the RPN2-mediated inhibitory effect on the glioma malignant phenotype and TMZ sensitivity in vitro, we further performed an in vivo experiment using an LN229 xenograft model." (PMID 33087705, 2020). "Taken together, our data revealed a new miR-181c/RPN2/wnt/β-catenin signaling axis that plays significant roles in glioma tumorigenesis and TMZ resistance, and it represents a potential therapeutic target, especially in GBM." (PMID 33087705, 2020). "Based on explicit RPN2 upregulation both primary and recurrent gliomas, we explored the RPN2-mediated effect on the glioma malignant phenotype and the chemosensitivity to TMZ." (PMID 33087705, 2020). "The analysis of the prognostic significance from primary and recurrent gliomas also indicated that RPN2 overexpression predicted poor prognosis." (PMID 33087705, 2020). "The focus of this project was to analyze the anti-cancer role of circNFIX in glioma and explore the novel ceRNA network of circNFIX/miR-378e/RPN2." (PMID 31888753, 2019). "In conclusion, our study on the oncogenic role of circNFIX in glioma showed that knockdown of circNFIX suppressed progression of glioma in vitro and in vivo, possibly by regulating miR-378e/RPN2 axis as a ceRNA." (PMID 31888753, 2019).